TIGD2 (tigger transposable element derived 2)
Synonyms: HEL106
Tractability: PROTAC: ubiquitination databases record sites on it.
Gene: Protein-coding gene on chromosome 4 (89,111,533 to 89,114,901, forward strand). Ensembl gene ENSG00000180346.
Subcellular location: Nucleus
Subcellular location (Human Protein Atlas): Nuclear bodies
Gene Ontology:
Molecular function: DNA binding; nucleic acid binding
Cellular component: nucleus
Genetic constraint (gnomAD): Loss-of-function variants: 22 observed, 42.53 expected, observed/expected ratio (o/e) 0.52, 90% interval 0.37 to 0.74. The upper end of that interval is the gene's LOEUF score, 0.74, which puts it in group 3 of 6, group 1 being the genes least tolerant of losing a copy. Missense variants: 590 observed, 648.7 expected, observed/expected ratio (o/e) 0.91, 90% interval 0.85 to 0.97. Synonymous variants: 201 observed, 221.06 expected, observed/expected ratio (o/e) 0.91, 90% interval 0.81 to 1.02.
Homologues: Orthologues: chimpanzee TIGD2 (99% identical), macaque TIGD2 (98% identical), dog TIGD2 (95% identical), pig TIGD2 (93% identical), mouse Tigd2 (88% identical), rat Tigd2 (87% identical), tropical clawed frog tigd3 (16% identical). Paralogues in human: JRKL (62% identical), JRK (32% identical), TIGD7 (28% identical), TIGD1 (28% identical), TIGD5 (24% identical), CENPB (23% identical), TIGD4 (22% identical), TIGD6 (22% identical), POGZ (16% identical), TIGD3 (15% identical), POGK (15% identical).
Diseases named in the same sentence as TIGD2 in open-access papers:
TIGD2 is named in the same sentence as 3 diseases in open-access papers, as found by Europe PMC text mining. Sharing a sentence is not in itself a finding about the gene and the disease. The quoted sentences say what the papers report.
fibrosarcoma (1 paper, 2022). A malignant mesenchymal fibroblastic neoplasm affecting the soft tissue and bone. "An additional four previously identified genes (RAPGEF2, SLC20A1, CO5A, TIGD2) were also more highly expressed in fibrosarcomas, but the comparison did not exceed the cutoff for significance used in the present study." (PMID 36099287, 2022).
bacterial infection (1 paper, 2023). "The TIGD2 gene has also been associated with resistance to disease and bacterial infection in cattle, making it an important candidate in our study." (PMID 37932811, 2023).
TIGD2 also shares sentences with these, for which no sentence is quoted: Parkinsonism (1 paper).